GPX7 (glutathione peroxidase 7)
Description:
Acts as an endoplasmic reticulum (ER) thiol peroxidase that maintains ER redox homeostasis and supports oxidative protein folding. Rapidly reacts with hydrogen peroxide to form sulfenylated/disulfide intermediates and oxidizes protein disulfide isomerase (PDI) family members, promoting disulfide-bond formation. Functions in a redox relay with ERO1A, using ERO1A-generated H(2)O(2) to drive PDI oxidation, linking peroxide detoxification to productive disulfide formation. Protects esophageal epithelia from hydrogen peroxide-induced oxidative stress by reducing reactive oxygen species (ROS) and preventing oxidative DNA damage and double-strand breaks.
Synonyms: GPx-7; GSHPx-7; GPX6; FLJ14777; NPGPx; CL683
Tractability: Antibody: UniProt places it where antibodies can reach, with high confidence; UniProt predicts a signal peptide or a membrane-spanning region; its Gene Ontology location is reachable by antibodies, with medium confidence. PROTAC: its protein half-life has been measured.
Gene: Protein-coding gene on chromosome 1 (52,602,371 to 52,609,051, forward strand). Ensembl gene ENSG00000116157.
Subcellular location: Endoplasmic reticulum
Pathways (Reactome):
Cellular responses to stimuli: Detoxification of Reactive Oxygen Species
Gene Ontology:
Molecular function: catalase activity; peroxidase activity; protein binding; glutathione peroxidase activity; protein disulfide isomerase activity
Biological process: cellular response to oxidative stress; cellular oxidant detoxification; response to oxidative stress
Cellular component: endoplasmic reticulum; endoplasmic reticulum lumen
Genetic constraint (gnomAD): Loss-of-function variants: 23 observed, 20.71 expected, observed/expected ratio (o/e) 1.11, 90% interval 0.8 to 1.57. The upper end of that interval is the gene's LOEUF score, 1.57, which puts it in group 6 of 6, group 1 being the genes least tolerant of losing a copy. Missense variants: 238 observed, 224.17 expected, observed/expected ratio (o/e) 1.06, 90% interval 0.95 to 1.18. Synonymous variants: 112 observed, 97.36 expected, observed/expected ratio (o/e) 1.15, 90% interval 0.99 to 1.35.
Homologues: Orthologues: chimpanzee GPX7 (100% identical), macaque GPX7 (95% identical), pig GPX7 (94% identical), rabbit GPX7 (89% identical), mouse Gpx7 (89% identical), guinea pig GPX7 (88% identical), dog GPX7 (87% identical), rat Gpx7 (86% identical), tropical clawed frog gpx7 (71% identical), zebrafish gpx7 (65% identical), Caenorhabditis elegans gpx-2 (28% identical), Caenorhabditis elegans gpx-5 (27% identical), and 3 more. Paralogues in human: GPX8 (50% identical), GPX4 (35% identical), GPX1 (34% identical), GPX5 (32% identical), GPX2 (29% identical), GPX6 (28% identical), GPX3 (28% identical).
Diseases named in the same sentence as GPX7 in open-access papers:
GPX7 is named in the same sentence as 61 diseases in open-access papers, as found by Europe PMC text mining. Sharing a sentence is not in itself a finding about the gene and the disease. The quoted sentences say what the papers report.
Barrett esophagus (9 papers, 2010 to 2025). Esophageal lesion lined with columnar metaplastic epithelium which is flat or villiform. "The dysfunction of GPX7 in esophageal cells increases ROS levels and oxidative DNA damage, which are common risk factors for Barrett's esophagus and EAC." (PMID 27206673, 2016). "GPX7, for example, is frequently silenced in esophageal adenocarcinoma and impacts its capacity in regulating ROS and oxidative DNA damage." (PMID 37507854, 2023). "An earlier study has shown that GPX7 has potential tumor suppressor functions in esophageal adenocarcinoma." (PMID 28903346, 2017). "Of note, silencing of GPX7 by promoter hypermethylation is a frequent finding in Barrett's dysplasia and esophageal adenocarcinomas." (PMID 28903346, 2017). "Barrett’s esophagus is accompanied by a decreased expression of glutathione peroxidase 7 (GPX7)." (PMID 37408240, 2023). "Gpx7 is silenced in Barrett's oesophagus and adenocarcinoma via epigenetic mechanisms." (PMID 20932318, 2010).
glioma (8 papers, 2021 to 2024). A benign or malignant brain and spinal cord tumor that arises from glial cells (astrocytes, oligodendrocytes, ependymal cells). "GPX7 silencing enhances oxidative stress associated with ferroptosis in glioma cells, while GXP7 deletion sensitizes gliomas to ferroptosis induced by erastin." (PMID 36937406, 2023). "To better understand the underlying molecular mechanisms by which GPX7 modulates the biological processes in gliomas, we screened out the GPX7 co-expressed gene signatures by the LinkFinder module in the LinkedOmics." (PMID 35440701, 2022). "Combining these multiple data, we provided the first evidence regarding the epigenetic-mediated regulatory mechanisms underlying GPX7 activation in gliomas." (PMID 35440701, 2022). "We discovered that GPX7 was remarkably increased in glioma tissues and cell lines, and was associated with poor prognosis." (PMID 35440701, 2022). "In summary, our results indicate that the overall GPX7 expression varied significantly as a function of histopathological grade and is highly associated with glioma progression." (PMID 35440701, 2022). "On the other hand, the role of GPX7 in the development of gliomas and the epigenetic mechanisms underlying this process have yet to be fully characterized." (PMID 35440701, 2022). "Herein, our findings provide insights into understanding the epigenetic regulation and the potential association of GPX7 with clinical features and immunity of gliomas." (PMID 35440701, 2022). "Ferroptosis-related assays were carried out to investigate the association between GPX7 and ferroptosis in glioma." (PMID 35127512, 2021). "What is more, high GPX7 expression remains associated with poor prognosis of glioma patients (p < 0.05)." (PMID 33750478, 2021). "Univariate and multivariate Cox analysis confirmed that GPX7 was an independent risk factor for glioma patients." (PMID 33750478, 2021). "These authors conclude that the overall GPx-7 expression varied significantly as a function of histopathological grade, is highly associated with glioma progression, and correlates with an unfavorable prognosis in adult low-grade glioma tumors." (PMID 37761814, 2023). "We next explored the genes significantly associated with GPX7 and their functions in gliomas." (PMID 35440701, 2022). "Notably, we provided the first evidence regarding the epigenetic-mediated regulatory mechanisms underlying GPX7 activation in gliomas." (PMID 35440701, 2022). "Thus, we naturally extended our analysis to other glioma datasets, and in all of them, we consistently found that overexpression of GPX7 was associated with a worse prognosis." (PMID 35440701, 2022). "As a result, we found that GPX7 could still be used as an independent risk factor in predicting the prognosis of glioma patients after excluding the influence of other factors." (PMID 33750478, 2021). "In our study, we found that the loss of GPX7 resulted in decreased GSH level in glioma cells." (PMID 35127512, 2021). "The GPX7 was recommended as an independent risk factor for patients diagnosed with glioma for the first time and GPX7 could be potentially used as the therapy target in future." (PMID 33750478, 2021). "In addition, the combination of GPX7 deficiency and erastin treatment showed a remarkable synergistic effect on the induction of ferroptosis of glioma." (PMID 35127512, 2021). "Whether GPX7 can be used as an independent risk factor for glioma patients remains unclear." (PMID 33750478, 2021). "Furthermore, to verify whether GPX7 can be used as an independent risk factor in predicting the prognosis of glioma patients, the Cox regression model was used to assess GPX7 expression and other clinical features." (PMID 33750478, 2021). "A bioinformatics study revealed that elevated GPX7 is involved in the progression of glioma through several enriched pathways, including the cell-cycle pathway, focal adhesion pathway, and toll-like receptor pathway." (PMID 39125992, 2024).
glioma (continued). "It has recently been found that GPX7 expression is a potential prognostic biomarker in lower-grade glioma." (PMID 39125992, 2024). "In fact, GPx-7 expression was higher in glioblastoma than in low-grade gliomas (oligoastrocytoma, oligodendroglioma, and astrocytoma), while the expression of GPx-7 was higher as the pathological grade increased." (PMID 37761814, 2023). "In this regard, we next sought to uncover the molecular mechanisms that contribute to the high expression of GPX7 in gliomas." (PMID 35440701, 2022). "Despite the controversial role of GPX7 in carcinogenesis, there is limited literature on the potential mechanisms of GPX7 expression in gliomas." (PMID 35440701, 2022). "In conclusion, we have shown that GPX7 overexpression has an oncogenic role and was related to worse clinical evolution in gliomas." (PMID 35440701, 2022). "GPX7 was found to be higher in gliomas, especially in astrocytic, oligodendroglial and mixed gliomas." (PMID 35440701, 2022). "Leveraging the TCGA and CGGA datasets, we next explored the correlation between GPX7 expression and the clinicopathological/molecular parameters of gliomas (WHO grade 2–4)." (PMID 35440701, 2022). "We consistently showed that GPX7 was overexpressed in gliomas compared to normal samples in all datasets." (PMID 35440701, 2022). "Accordingly, the vast majority of glioma cell lines highly expressed GPX7 and this overexpression was cell cycle-dependent manner." (PMID 35440701, 2022). "Together, these findings support the idea that changes in GPX7 expression levels are likely related to the induction of oxidative stress and ROS-mediated cell injury induced by distinct drugs approved to treat gliomas." (PMID 35440701, 2022). "Here, we investigated the molecular and clinical features of GPX7 in glioma through bioinformatics analysis." (PMID 33750478, 2021). "GPX7 silencing enhanced ferroptosis-related oxidative stress in glioma cells and the loss of GXP7 sensitized glioma to ferroptosis induced by erastin." (PMID 35127512, 2021). "For the first time, the GPX7 was reported as a carcinogenic gene in glioma, and our results revealed the correlation between gliomas and malignant clinical features." (PMID 33750478, 2021). "For further verification, 5 glioma samples and 5 normal brain tissue samples were used to verify the expression level of GPX7 by RT-qPCR." (PMID 33750478, 2021). "The expression of GPX7 was validated in glioma and normal brain tissues by RT-qPCR to compensate for the insufficiency of sample information in the database." (PMID 33750478, 2021). "Integrating bioinformatic analysis and experimental analysis allow more effective contributions to the promising target of GPX7 in glioma." (PMID 35127512, 2021). "As a result, the expression of GPX7 in gliomas was higher compared to that in normal tissues (p < 0.05), which corroborated with the findings from previous analysis of the CGGA database." (PMID 33750478, 2021). "Based on the regulatory effect of GPX7 on ferroptosis-related oxidative stress, we then investigated the GPX7 mediated effect on glioma development and sensitivity to erastin." (PMID 35127512, 2021). "Nonetheless, the mechanism of GPX7 in regulating the malignant behavior of glioma remains controversial." (PMID 33750478, 2021). "GPX7 knockdown mediated enhancement of ferroptosis-related oxidative stress promoted glioma ferroptosis induced by erastin." (PMID 35127512, 2021). "In glioma, only one bioinformatic study reported that GPX7 was a potential prognostic molecule based on Chinese Glioma Genome Atlas (CGGA) database." (PMID 35127512, 2021). "By analyzing the data from the CGGA database, it was concluded that GPX7 is a novel oncogene, and its overexpression indicated a poor prognosis for gliomas." (PMID 33750478, 2021). "To better understand the roles of GPX7 in the immune microenvironment of glioma, we analyzed the correlations between GPX7 and several common immune cell types in TIMER." (PMID 35127512, 2021).
glioma (continued). "It is of pivotal importance to verify the reliability of GPX7 in predicting the OS of glioma patients by the ROC curve." (PMID 33750478, 2021). "In summary, these results revealed that miR-29b can sensitize glioma cells to erastin partially via GPX7." (PMID 35127512, 2021). "The overexpression of GPX7 in gliomas was further validated by the GEPIA database and it was associated with poor prognosis." (PMID 33750478, 2021). "In our study, multi-database analyses showed that GPX7 expression was upregulated in glioma and was an independent prognostic factor of glioma patients." (PMID 35127512, 2021). "CCK-8, wound healing, transwell and apoptosis flow cytometry assays were conducted to examine proliferative, migratory and invasive abilities of glioma cells with GPX7 knockdown alone or with GPX7 knockdown and erastin (10 μM) cotreatment." (PMID 35127512, 2021). "For the first time, through analysis of multidimensional data, we propose that GPX7 can be used as a novel oncogene to shorten the prognosis of glioma patients." (PMID 33750478, 2021). "The results indicated that the expression of GPX7 in glioma was higher compared to that in normal brain tissue." (PMID 33750478, 2021). "Through the correlation analysis between GPX7 and OS of glioma patients, we discovered that the is the expression of GPX7 was negatively related with the OS in glioma patients." (PMID 33750478, 2021). "CCK8, wound healing, transwell and cell apoptosis assays were performed to explore the functions of GPX7 in glioma cells." (PMID 35127512, 2021). "GPX7 is considered as a novel molecular marker that predicts the prognosis of glioma patients, with high validity and reliability." (PMID 33750478, 2021). "GPX7 was aberrantly expressed in glioma and higher expression of GPX7 was correlated with adverse outcomes." (PMID 35127512, 2021). "Univariate and multivariate Cox regression analyses confirmed that the expression value of GPX7 was an independent prognostic factor in glioma." (PMID 33750478, 2021). "To explore how GPX7 affects glioma patients, we separated the obtained samples into high GPX7 expression group and a low GPX7 expression group." (PMID 33750478, 2021). "As such, to reveal the role of GPX7 in glioma, this work first obtained RNA sequencing data of more than one thousand glioma patients from the CGGA database." (PMID 33750478, 2021). "In TCGA, Kaplan-Meier survival analyses showed that glioma patients with GPX7-high had a worse prognosis than that with GPX7-low." (PMID 35127512, 2021). "These pathways were thus considered as potential strategies for GPX7 to achieve its regulation in glioma." (PMID 33750478, 2021). "Gene Set Enrichment Analysis (GSEA) was applied to investigate the GPX7-related functions in glioma." (PMID 33750478, 2021). "It has been described that GPx-7 is higher in gliomas, especially in astrocytic, oligodendroglial, and mixed gliomas, supporting the data described here and settling the idea that gpx7 overexpression may be involved in glioma tumorigenesis." (PMID 37761814, 2023). "GPX7 is closely related to the malignant clinical features of gliomas from CCGA." (PMID 36052280, 2022). "Based on these results, it is conceivable that the correlation of immune cells and GPX7 expression may be characteristic of tumor/tissue type, which emphasizes the uniqueness of immune infiltration in gliomas." (PMID 35440701, 2022). "In this study, we hypothesized that GPX7 methylation status could influence biological functions and local immune responses that ultimately impact prognosis in adult gliomas." (PMID 35440701, 2022). "To address this issue, in the present study, we used database research and bioinformatic analyses to assess the expression of GPX7 in gliomas and analyze its epigenetic modulation, potential biological functions, prognostic value and correlation with tumor-infiltrating immune cells." (PMID 35440701, 2022).
glioma (continued). "However, we found that the high expression of GPX7 accounts for malignant progression of glioma by comparing the overall survival time between the two groups and verifying its credibility via ROC curves." (PMID 33750478, 2021). "Bioinformatics method was used to assess the prognostic role of GPX7 in glioma." (PMID 35127512, 2021). "However, the combination of GPX7 knockdown and erastin treatment significantly suppressed the proliferation of glioma cells." (PMID 35127512, 2021). "The enrichment of GPX7 in these pathways revealed that glioma might participate in the regulation via various complex pathways." (PMID 33750478, 2021). "GSEA analysis suggested that GPX7 might involve in joining the pathophysiological process of glioma." (PMID 33750478, 2021). "GSEA was employed to find the biological functions of GPX7 in glioma." (PMID 35127512, 2021). "Based on algorithm prediction and experimental validation, our work found that miR-29b could directly inhibit GPX7 post-transcriptionally, exerting similar ferroptosis induction effect on glioma, synergizing with erastin treatment." (PMID 35127512, 2021). "Meanwhile, we attempted to reveal the GPX7-related pathological progress in gliomas." (PMID 33750478, 2021). "Here, we aimed to explore the molecular and biological function characteristics of GPX7 in glioma." (PMID 33750478, 2021). "Based on the antioxidative functions and complex roles of GPX7 in tumors, we speculate that GPX7 may participate in glioma development by regulating ferroptosis, which need to be further verified." (PMID 35127512, 2021). "Given GPX7 being a direct target of miR-29b, we then investigated whether miR-29b also regulates ferroptosis-related oxidative stress in glioma cells." (PMID 35127512, 2021). "We speculated that an external stimuli of oxidative stress, for instance erastin treatment, may be required for GPX7 targeting therapy of glioma." (PMID 35127512, 2021). "Similarly, restoration of GPX7 following transfection with miR-29b mimic can reverse the miR-29b and erastin mediated synergistic inhibitory effects on glioma cells." (PMID 35127512, 2021). "Our study clarified the prognostic role of GPX7 in glioma and preliminarily revealed the role of GPX7 in ferroptosis, which may be conducive to the exploration of therapeutic targets of glioma." (PMID 35127512, 2021). "Furthermore, GPx-7 is overexpressed in aggressive gliomas, which also suggests that GPx-7 may be involved in the malignant progression of gliomas." (PMID 37761814, 2023). "However, the epigenetic mechanisms that potentially modulate GPX7 expression in gliomas are still unknown." (PMID 35440701, 2022). "In addition, GPX7 expression increased in chemotherapy-resistant GBM patients, supporting the idea that changes in GPX7 expression are likely to be related to the induction of oxidative stress and ROS-mediated cell injury induced by specific drugs approved to treat gliomas." (PMID 35440701, 2022). "However, little is known about the function of GPX7 in gliomas." (PMID 35440701, 2022). "Furthermore, our study yields critical insights into the significant effect of GPX7 in modulating the immune molecules and immune cell infiltration in the microenvironment of gliomas, impacting patient outcomes, opening up future opportunities to regulate the immune response." (PMID 35440701, 2022). "The result suggested that GPX7 might promote the expression of genes that are positively correlated with its expression level or that these co-expressed positively related genes co-promote or inhibit specific pathophysiological processes with GPX7 to promote the occurrence and development of glioma." (PMID 33750478, 2021). "All in all, suppressing GPX7 could be a valuable strategy for glioma treatment." (PMID 35127512, 2021). "Additionally, some immune cells were positively correlated with GPX7 expression in glioma." (PMID 35127512, 2021).